RNU6-1048P (RNA, U6 small nuclear 1048, pseudogene)
Gene: Small nuclear RNA gene on chromosome 2 (43,892,690 to 43,892,796, forward strand). Ensembl gene ENSG00000200924.
Homologues: Orthologues: chimpanzee U6 (98% identical), macaque U6 (92% identical), dog U6 (78% identical), guinea pig U6 (67% identical). Paralogues in human: RNU6-154P (90% identical), RNU6-1 (89% identical), RNU6-1152P (89% identical), RNU6-116P (89% identical), RNU6-11P (89% identical), RNU6-14P (89% identical), RNU6-15P (89% identical), RNU6-19P (89% identical), RNU6-2 (89% identical), RNU6-211P (89% identical), RNU6-37P (89% identical), RNU6-3P (89% identical), and 1287 more.